MPO (myeloperoxidase)
Diseases named in the same sentence as MPO in open-access papers (continued):
Sharing a sentence is not in itself a finding about the gene and the disease.
gastritis (14 papers, 2008 to 2025). Inflammation of the stomach. "For example, a prior study showed that iodoacetamide-induced gastritis was associated with increased gastric mucosal injury and elevated local MPO activity." (PMID 40943779, 2025). "For instance, it has been reported that H. pylori neutrophil-activating protein may increase MPO release from neutrophils, contributing to the pathogenesis of H. pylori-associated gastritis." (PMID 40943779, 2025). "Neutral corn protein hydrolysate attenuated gastritis through reduction of MPO, IL-1β, IL-6, KC, TNF-α, and MCP-1." (PMID 40264171, 2025). "Helicobacter pylori infection, a critical factor in gastritis, induces ROS release from neutrophils, which, processed by myeloperoxidase, forms the oxidant hypochlorite anion." (PMID 39385181, 2024). "The results indicated that in H. pylori-positive patients with gastritis, the serum levels of myeloperoxidase, neutrophil elastase, MMP-8, and MMP-9 increased significantly." (PMID 37605137, 2023). "A number of studies have reported a significant correlation between the 13C-UBT and H. pylori bacterial load grade of gastritis activity, and gastric mucosal myeloperoxidase activity that is a quantitative marker of gastrointestinal inflammation." (PMID 32153909, 2018). "Neutrophil marker MPO immunostaining of neutrophils was carried out on a gastric cancer, gastric cancer adjacent tissue array (Array 1) and a gastric cancer and gastritis tissue array (Array 2)." (PMID 27412620, 2016). "Furthermore, gastric mucosal damage and MPO activity were significantly diminished in the Rb-ME-administrated group of the gastritis model." (PMID 32260181, 2020). "These hypotheses suggest the possibility that MPO secreted from activated neutrophils in H. pylori-mediated gastritis lesions may induce LDL oxidation." (PMID 27148410, 2016). "Notably, it has been reported that in a H. pylori-induced gastritis model, MPO activity exhibited an opposite trend to PGI levels, further suggesting that MPO may mediate PGI-associated gastric lesions." (PMID 40547041, 2025). "Furthermore, a significant interaction between the factors treatment and gender in MPO activity may suggest there is a gender difference in sensitivity of IAA-induced gastritis." (PMID 24345032, 2013). "Additionally, PDG derived from a marine sponge-associated actinomycete decreased the levels and expression of various inflammatory markers, including myeloperoxidase, IL-1β, TNF-α, iNOS, Cox-2, and NF-κB in a murine gastritis model." (PMID 35336729, 2022). "Myeloperoxidase (MPO) released from inflammatory cells and manganese superoxide dismutase 2 (SOD2) enhance inflammation and tissue damage, thereby increasing the severity of chronic atrophic gastritis." (PMID 18253117, 2008).
malaria (14 papers, 2012 to 2025). Malaria is a serious and sometimes fatal disease caused by a parasite that commonly infects a certain type of mosquito which feeds on humans. "Neutrophils may be involved in the development of complications associated with malaria by releasing toxic granules containing enzymes such as myeloperoxidase, neutrophil elastase, and matrix metalloproteinase-8 (MMP-8)." (PMID 39598252, 2024). "Transcripts of genes encoding neutrophil granule protein MPO and ELANE were expressed at higher levels in concurrent CM and SMA in comparison to uncomplicated malaria, and separately in comparison to cases of CM alone." (PMID 40383794, 2025). "Increased myeloperoxidase activity is a marker of increased neutrophil activation in malaria disease; therefore, an increase in granulocyte number in peripheral blood is observed when coupled with leukocyte hemozoin accumulation." (PMID 39683816, 2024). "Blood samples were collected and used diagnose malaria parasite using the rapid test followed by Giemsa stain microscopy and have the full blood count and MPO level using a colorimetric method." (PMID 36658587, 2023). "The present work aimed at investigating the modulating effect of ellagic acid and its analogues on the redox activity of neutrophils and myeloperoxidase involved in malaria onsets." (PMID 37298992, 2023). "Clinical symptoms including haemoglobin concentration, WBC counts, platelet cell count and level of plasma MPO in malaria infected patients were significantly related to the altitudes." (PMID 36658587, 2023). "This work aimed at investigating the modulatory effect of ellagic acid and its analogues on the redox activity of neutrophils and myeloperoxidase involved in malaria." (PMID 37298992, 2023). "This study aimed to investigate the malaria distribution and its relationship with level of some blood parameters and plasma myeloperoxidase (MPO) in population of three localities with different altitudes." (PMID 36658587, 2023). "The distinct correlations of NE with bacterial 16S copies as well as the differences in MPO expression between the Mcpt4-/- and Mcpt4+/+ mice suggest a novel role for Mcpt4 in neutrophil regulation in the context of malaria." (PMID 35154114, 2022). "In the malaria group as a whole, MPO, sCD14 and in particular sCD25 were correlated with disease severity." (PMID 30563486, 2018). "While other report evaluated activation of polymorphonuclear cells and observed elevated levels of myeloperoxidase, lysozyme and lipocalin in patients with severe malaria, the involvement of neutrophils in malaria pathogenesis has been poorly investigated." (PMID 22745844, 2012). "Malaria patients in Bamenda and Bambili recorded higher MPO levels than patients in Santa." (PMID 36658587, 2023). "Herein we extend these findings by showing enhanced activation of neutrophils, T-cells and monocyte/macrophages as assessed by the soluble activation markers MPO, sCD25, sCD14 and sCD163, with particular high levels of MPO and sCD25 in malaria patients that were co-infected with HIV." (PMID 30563486, 2018). "Incorporation of additional neutrophil activation markers, e.g., myeloperoxidase, lysozyme and neutrophil-specific granule proteins, and pro-inflammatory chemokines may further elucidate involvement of neutrophil activation in knowlesi malaria pathogenesis." (PMID 39150978, 2024). "A recent study of Plasmodium yoelii non-lethal infection in wild-type and MPO deficient mice as a murine malaria model, suggested that MPO could contribute to a protective anti-parasite response." (PMID 30563486, 2018). "CIC levels were substantially elevated in approximately 75% of malaria cases tested here and positively correlated with anti-PF4/P, as well as with MPO, parasite cfDNA, sST2, and sCD62p in Ret+ CM." (PMID 38652559, 2024). "Levels of sCD25 and MPO increased gradually from patient with HIV only to patient with malaria only, with the highest levels in the HIV/malaria group." (PMID 30563486, 2018).
malaria (continued). "Five biomarkers showed the highest AUROC in all malaria patients compared to the control group: CRP (1.00), MPO (0.99), D-dimers (0.98), elastase-2 (0.98), and sICAM-1 (0.98)." (PMID 23866258, 2013). "With respect to study areas, malaria positive and negative patients showed a significant difference in MPO (p = 0.003)." (PMID 36658587, 2023). "First, sCD25, reflecting T-cell activation, and MPO, reflecting neutrophil activation, showed a gradual increase from the group with isolated HIV infection to the group with malaria and with the highest levels in the group with HIV and malaria co-infection." (PMID 30563486, 2018). "In HIV-infected patients co-infected with P. falciparum there was a significant decline in MPO, sCD25 and sCD14 levels during follow-up, and for MPO, this was also seen for malaria patients without HIV infection." (PMID 30563486, 2018). "PAPP-A and myeloperoxidase had not been tested in malaria before." (PMID 23866258, 2013). "Here we extend these findings by showing that HIV-infected patients with falciparum malaria have markedly raised levels of MPO and sCD25 as compared with both malaria patients without HIV infection and HIV-infected patients without malaria." (PMID 30563486, 2018).
ovarian carcinoma (14 papers, 2013 to 2026). A malignant neoplasm originating from the surface ovarian epithelium. "In accordance, a polymorphism of the MPO gene downregulating its expression is associated with decreased lung, breast and ovarian cancer risk." (PMID 33916434, 2021). "Particularly, a study of human ovarian cancer detected a polymorphism associated with elevated MPO expression in several low-stage carcinomas, suggesting a role of MPO-mediated oxidative burst in cancer development." (PMID 33916434, 2021). "Other studies have found a SNP in MnSOD (rs4880) and a SNP in MPO (rs2333227) to be associated with increased risk for ovarian cancer." (PMID 26301412, 2015). "Recent genetic studies have linked MPO to lung and ovarian cancers by demonstrating a striking correlation between the relative risk for development of the disease and the incidence of functionally distinct MPO polymorphisms." (PMID 26301412, 2015). "Studies have found that MPO expression can be detected in the serum of ovarian cancer patients at different stages, while it is undetectable in healthy individuals." (PMID 40547041, 2025). "Myeloid cells express MPO in a dimeric form, while the authors found the unique expression of only the monomeric form of MPO in OC cells, tissues and blood of an ovarian cancer patients." (PMID 37513924, 2023). "According to several experimental reports, high MPO levels have been detected in ovarian cancer cells." (PMID 36903316, 2023). "What is also interesting iNOS expression was in strict correlation with myeloperoxidase (MPO) expression, and silencing MPO gene also resulted in significant induction of ovarian cancer cells apoptosis." (PMID 30970628, 2019). "High MPO positive cell density enhances the indicative value of IL-17 for response to chemotherapy in ovarian carcinoma." (PMID 27531373, 2016). "This study focuses on the predictive value of myeloperoxidase (MPO) concerning response to chemotherapy of ovarian cancer." (PMID 27531373, 2016). "Overexpression of MPO has been detected in ovarian cancer, and silencing of MPO gene expression induced apoptosis in cancer cells through activation of caspase-3." (PMID 24391750, 2013). "Since many studies have shown an increase in the expression of MPO in ovarian cancer tissues, the study of compounds that could potentially inhibit the activity of this enzyme is very important." (PMID 37513924, 2023). "Many recent data reported an elevation in MPO levels of ovarian cancer cells." (PMID 31202269, 2019). "Additionally, in another study we were able to show that high density of myeloperoxidase (MPO) positive cell enhances the indicative value of IL-17 for response to chemotherapy in ovarian carcinoma." (PMID 29661166, 2018). "Moreover, silencing of MPO has been shown to effectively induce apoptosis in ovarian cancer cell lines by increasing caspase-3 activity." (PMID 28183295, 2017). "There are few studies reporting the prognostic and predictive role of MPO in ovarian cancer." (PMID 27531373, 2016). "Elevated expression of inducible nitric oxide synthase (iNOS), myeloperoxidase (MPO), NAD(P) H oxidase, and nitric oxide (NO) as well as lowered apoptosis have been observed in ovarian cancer tissues." (PMID 31202269, 2019). "In addition to defective apoptosis, nitric oxide (NO), myeloperoxidase (MPO), NAD(P)H oxidase, and extended combinations of these enzymes have all been observed in ovarian cancer tissues." (PMID 36903316, 2023).
Sjögren’s syndrome (14 papers, 2014 to 2025). "Moreover, MPO was a target of drugs in five clinical trials evaluating their effectiveness in the treatment of xerostomia, head and neck cancer oral complications, and Sjögren’s Syndrome (NCT02430298, NCT00057785, NCT03953703, NCT04392622, and NCT02990468)." (PMID 35268532, 2022). "A number of OS- and NS-related hallmarks characterize Sjøgren's syndrome (SS) patients, including excess protein carbonyls and AGEs, 4-HNE, TNF-α, MPO, and 3-NT; moreover, excess 8-OHdG and hexanoyl-lysine were found in SS patients." (PMID 24876913, 2014).
Cirrhosis (13 papers, 2005 to 2025). A chronic disorder of the liver in which liver tissue becomes scarred and is partially replaced by regenerative nodules and fibrotic tissue resulting in loss of liver function. "This study also provides evidence for the involvement of oxidative stress in the cell injury occurring in CCl4-induced cirrhosis associated with iron and copper overload and an increase of myeloperoxidase and iNOS expression." (PMID 15745444, 2005). "Consistent with the previous findings, the ACLF group exhibited an increase in MPO activity compared to the control and cirrhosis groups." (PMID 38396750, 2024). "A similar pattern with higher H3Cit-DNA and MPO-DNA levels in Child–Pugh B or C patients compared to Child–Pugh A patients was also seen when only comparing patients with cirrhosis." (PMID 34504150, 2021). "MPO concentration was shown to differentiate patients with hepatocellular carcinoma from those with chronic hepatitis or severe cirrhosis in the context of hepatitis C39." (PMID 25666092, 2015). "The use of H3Cit-DNA instead of the previously more commonly used MPO-DNA provides a new insight into NET formation in cirrhosis by increasing specificity, since MPO-DNA could in theory form independently of NET formation." (PMID 34504150, 2021). "Consistently, immunohistochemistry (IHC) for the neutrophil marker MPO and the NETs marker MPO-H3Cit in an independent HCC cohort with advanced cirrhosis from our institute also demonstrated a higher distribution of neutrophils and NETs." (PMID 38388466, 2024). "Before summarizing our knowledge about the defective neutrophil functions in cirrhosis, it is important to have some general information on NADPH oxidase activity and MPO release in neutrophils." (PMID 31134093, 2019). "They found that the presence of HCC did not further increase the plasma levels of MPO-DNA or CitH3 as compared to Child–Pugh B and C cirrhosis." (PMID 41516032, 2025). "A decreased number of neutrophils producing MPO and reduced intracellular MPO levels have been observed in neutrophils isolated from patients with compensated cirrhosis, but not from those with ACLF." (PMID 37822786, 2023). "Another study reported that intracellular MPO content is not altered in neutrophils from patients with cirrhosis but that its extracellular release in response to fMLF is decreased." (PMID 37822786, 2023). "MPO-DNA, H3Cit-DNA, and thrombin–antithrombin (TAT) complex, as a marker of coagulation activity, were measured using ELISA in plasma from 82 patients with HCC, 95 patients with cirrhosis and 50 healthy controls." (PMID 34504150, 2021). "Unexpectedly, we found that the presence of HCC did not further increase the plasma levels of MPO-DNA or H3Cit-DNA as compared to the corresponding patients with cirrhosis only." (PMID 34504150, 2021). "Studies have shown that neutrophils from patients with cirrhosis exhibit ex vivo defective adenine dinucleotide phosphate (NADPH) oxidase 2 (NOX2) and of myeloperoxidase (MPO) exocytosis, which both may contribute to the susceptibility to infection in patients with cirrhosis." (PMID 31134093, 2019). "Therefore, NETosis would not be expected to occur in neutrophils from patients with cirrhosis which have defect in NADPH oxidase and in MPO exocytosis." (PMID 31134093, 2019).
colon cancer (13 papers, 2013 to 2025). "MPO has been implicated in the pathogenesis of several types of cancer including breast and colon cancer due to oxidative biproducts which are mutagenic." (PMID 38004170, 2023). "In the colonic mucosa, MPO activity correlates with the severity of colitis and is an indicator of colon cancer risk." (PMID 28448444, 2017). "Additionally, when retinal or colon cancer cell lines or human umbilical vein endothelial cells are cocultured with neutrophils, MPO migrates into these cells to cause cytotoxicity." (PMID 38916955, 2024). "Thus, neutrophils act on colorectal carcinogenesis also influencing the complex effects of diet on colon cancer risk by the endogenous generation, through the MPO action, of acrolein, an oxidative by-product derived from unsaturated fats, serine, or threonine." (PMID 28448444, 2017). "In contrast, the tumor and plasma levels of MPO‐NDA were significantly decreased by SKAP1 knockdown in a mouse model of SW620 colon cancer." (PMID 39269257, 2024). "Our results also demonstrated that apigenin inhibited CAC by reducing neutrophil infiltration and levels of colon cancer markers, MPO, inflammatory cytokines, and COX-2." (PMID 29245972, 2017). "In our case, MN and MPO-ANCA-GN were diagnosed simultaneously, but the long duration of the proteinuria and the colon cancer suggested the possibility of malignancy associated-MN which presumably preceded MPO-ANCA-GN at least to some extent." (PMID 23537120, 2013). "Also, MPO activity categorized as the most specific inflammatory marker expressed as a result of colon cancer induction." (PMID 34711004, 2021). "There was no recurrence of colon cancer and MPO-ANCA remained negative during the follow-up." (PMID 23537120, 2013).